TEDC1 (tubulin epsilon and delta complex 1)
Description:
Acts as a positive regulator of ciliary hedgehog signaling. Required for centriole stability (By similarity). May play a role in counteracting perturbation of actin filaments, such as after treatment with the actin depolymerizing microbial metabolite Chivosazole F.
Synonyms: C14orf80
Tractability: PROTAC: ubiquitination databases record sites on it.
Gene: Protein-coding gene on chromosome 14 (105,489,855 to 105,499,575, forward strand). Ensembl gene ENSG00000185347.
Subcellular location: Cell projection, cilium; Cytoplasm, cytoskeleton, microtubule organizing center, centrosome, centriole
Subcellular location (Human Protein Atlas): Golgi apparatus; Cytosol; Nucleoplasm
Gene Ontology:
Molecular function: protein binding
Biological process: cytoskeleton organization; microtubule cytoskeleton organization; positive regulation of smoothened signaling pathway
Cellular component: centrosome; centriole; cilium
Genetic constraint (gnomAD): Loss-of-function variants: 52 observed, 46.99 expected, observed/expected ratio (o/e) 1.11, 90% interval 0.88 to 1.39. The synonymous counts are far from expectation, so gnomAD's model fits this gene poorly and the ratio says little. Missense variants: 724 observed, 590.82 expected, observed/expected ratio (o/e) 1.23, 90% interval 1.15 to 1.3. Synonymous variants: 352 observed, 249.55 expected, observed/expected ratio (o/e) 1.41, 90% interval 1.29 to 1.54.
Homologues: Orthologues: chimpanzee TEDC1 (99% identical), macaque TEDC1 (77% identical), pig TEDC1 (60% identical), guinea pig TEDC1 (58% identical), mouse Tedc1 (57% identical), rat Tedc1 (56% identical), tropical clawed frog TEDC1 (29% identical).
Diseases named in the same sentence as TEDC1 in open-access papers:
TEDC1 is named in the same sentence as 1 disease in open-access papers, as found by Europe PMC text mining. Sharing a sentence is not in itself a finding about the gene and the disease. The quoted sentences say what the papers report.
liver cancer (1 paper, 2022). An epithelial or non-epithelial malignant neoplasm that arises from the liver. "In Europeans, C10orf143 had a lower proportion of Neanderthal introgression among liver cancer patients compared to the general population and in East Asians, NENF and TEDC1 showed a similar pattern." (PMID 36503519, 2022). "In East Asians, there were two genes with a significant depletion of Neanderthal introgression in liver cancer patients compared to non-affected individuals—NENF (p-value = 3.32 × 10–8, adjusted p-value = 0.0001) and TEDC1 (p-value = 1.11 × 10–5, adjusted p-value = 0.038)." (PMID 36503519, 2022).